CD4 (CD4 molecule)
Diseases named in the same sentence as CD4 in open-access papers (continued):
Sharing a sentence is not in itself a finding about the gene and the disease.
HIV-1 infection (continued). "The differentiation of CCR5+CD4+ T cells is associated with the availability of IL-15, which increases during acute HIV-1 infection." (PMID 36821374, 2023). "HIV-1 infection is characterized by a progressive loss of peripheral blood CD4-positive (CD4+) T cells, an imbalance in CD4+ T-cell homeostasis, as well as a gradual deterioration of immune function." (PMID 36853052, 2023). "HIV-1 infection is known to activate caspases to eliminate infected CD4 T cells but also caused the death of bystander T cells." (PMID 36780482, 2023). "Acute HIV-1 infection in huNSG mice was associated with a profound decrease in CD4+ T cell percentages in the blood at day 24 when compared to animals sacrificed at day 10 post-infection." (PMID 36800238, 2023). "Although the association of CD4 with the DRM is unnecessary for HIV-1 infection, cholesterol depletion impairs HIV-1 entry." (PMID 37376566, 2023). "Recently, it has been evidenced that chronic HIV-1 infection gives rise to accelerated aging and it is associated with senescence in circulating CD4+ T cells." (PMID 37215829, 2023). "Latent viruses, such as cytomegalovirus (CMV) and Epstein-Barr virus (EBV), reactivate more frequently during HIV-1 infection due to the depletion of CD4+ T cells and loss of CD8+ T cells that control viral replication." (PMID 36672667, 2023). "Recent studies have shown spliced cell-associated viral RNA in CSF CD4 T cells during the acute stages of HIV-1 infection and weeks 2, 4, and 8 in SHIV-infected macaques, supporting active viral transcription within CSF CD4 T cells." (PMID 38060615, 2023). "With respect to specific variables associated with HIV-1 infection, decreased ratio of CD4/CD8 and male were independent risk factors for low HDL-C and high log (TG/HDL-C)." (PMID 37705002, 2023). "The level of activation and differentiation of CD4+ T cells, which are intrinsically regulated by cellular metabolism, has a critical impact on cell susceptibility to HIV-1 infection." (PMID 35205318, 2022). "Taken together, the loss of ISG15 expression restricted HIV-1 infection, not only in hTERT-immortalized fibroblasts, but also in primary human CD4+ T cells, the main target cell population of HIV-1." (PMID 35333911, 2022). "Here, we report two cases of VNPs who experienced the loss of CD4+ T-cell homeostasis (LoH) after more than 13 years of HIV-1 infection." (PMID 34668779, 2022). "In this study, we showed that the expression of CD98 was higher in HIV-1 latently infected cells than in uninfected cells, and CD98high CD4+ T cells are highly susceptible to HIV-1 infection." (PMID 36214569, 2022). "This suggests that HIV-1 infection primes CD4+ T cells to gain characteristics that are associated with TRM cells and adopt a TRM-like phenotypic signature." (PMID 35417711, 2022). "In particular, cellular activation and cell diversity are preserved and even in the absence of exogenous activation the key in vivo pathogenic properties of HIV-1 infection, robust viral replication and CD4+ T cell depletion, are observed." (PMID 35523829, 2022). "Primary CD4+ T cells with increased GLUT1 surface levels are more susceptible to productive HIV-1 infection and replication." (PMID 36467738, 2022). "Depending on Env tropism, MT-C34-positive CD4 lymphocytes were from 33- to 52-fold less susceptible to HIV-1 infection than MT-C34-negative cells in the KI group of samples but only 7-fold less sensitive upon LV transduction." (PMID 35073736, 2022). "Together, these results suggest that there is likely a set of ISGs in ISG15-deficient CD4+ T cells that is sufficient to reduce the susceptibility of primary CD4+ T cells to HIV-1 infection." (PMID 35333911, 2022). "Measurement of p24+ cells among different cells susceptible to HIV-1 infection in the humanized mouse model indicates a limitation of V3 mAb 2219 in controlling infection beyond CD4 T cells." (PMID 34986207, 2022).
HIV-1 infection (continued). "During the acute phase of HIV-1 infection, disruption of the gut mucosa, associated with depletion of CD4 T cells at the gut epithelium, is proposed to result in massive microbial translocation into the blood." (PMID 35287587, 2022). "We found ISG15 deficiency limits HIV-1 infection not only in fibroblasts, but also in human primary CD4+ T cells." (PMID 35333911, 2022). "Studies have confirmed that Th1/17 polarization enriched CD4 T cells have higher susceptibility to HIV-1 infection in in vitro and in vivo experiments." (PMID 35068272, 2022). "The majority of T cells die by pyroptosis, linking the HIV-1 infection and lymphopenia with dying CD4+ T cells releasing signals that cause more cells to die thus, preventing T cell homeostasis and renewal 31-33." (PMID 36313221, 2022). "They showed that ZFN specifically disrupted ~50% of CCR5 alleles in a pool of primary human CD4+ T cells, and that stable and heritable protection occurred against HIV-1 infection in vitro and in vivo in a NOG model of HIV infection." (PMID 35628210, 2022). "Analysis using the typing data indicated association of several HLA class I alleles on viral load an CD4 count in HIV-1 infection." (PMID 35653364, 2022). "Transitional and central memory T cells were slightly susceptible to HIV-1 infection, and effector memory CD4+ T cells, the most metabolically active T cell subset, showed the highest levels of HIV-1 infection." (PMID 36467738, 2022). "The study of HIV-1 infection using HLAC system highlighted the massive death caused by pyroptosis occurring in bystander CD4 T cells." (PMID 36000842, 2022). "Since death in HIV-1 infection is caused by immune deficiency directly correlated to CD4 depletion, CD4 count is in the causal pathway for death." (PMID 35707535, 2022). "Though DCs are less susceptible to HIV-1 infection than CD4+ T cells, they are among the first cells to encounter the virus after the infection across the mucosa and play a focal role in establishing HIV-1 infection and progression of the disease." (PMID 36146843, 2022). "For example, during HIV-1 infection, an expansion of adenoviruses in the gut has been demonstrated in association with a decrease in CD4+ T cell counts." (PMID 33952659, 2021). "These APCs will ultimately present HIV-1 antigens on MHC class II to CD4+ T cells with TCR specific to these HIV-1 antigens, leading to activated CD4+ T cells, which are now susceptible to HIV-1 infection and replication." (PMID 34344423, 2021). "Enhanced early activation and coexpression of CD38 and HLA-DR in TIGIT+NK cells were detected compared to TIGIT−NK cells, both of which were inversely associated with the decrease in CD4 T-cell counts in both acute and chronic HIV-1 infection." (PMID 33717085, 2021). "Further, as previously noted, the Nef-induced decrease in CD4 content of EVs was associated with an increased rate of HIV-1 infection of CD4+ T cells." (PMID 34290592, 2021). "A progressive loss of CD4+ T lymphocytes from blood, lymphoid organs and mucosal tissues is the hallmark of Human Immunodeficiency Virus 1 (HIV-1) infection." (PMID 34442703, 2021). "Taken together, this study reveals that NLRP3 inflammasome-dependent pyroptosis plays a key role in CD4 + T cell loss in patients with HIV-1 infections." (PMID 33883686, 2021). "An increased plasma viral load was observed after HIV-1 infection, which was associated with lower CD4+ T cell counts." (PMID 33952659, 2021). "The CD4+ NKT cells showed greater susceptibility, as compared to conventional CD4+ T cells, to HIV-1 infection owing to the elevated level of CCR5 coreceptor expression on iNKT cells." (PMID 34579186, 2021). "HIV-1 infection rapidly leads to a loss of the proliferative response of memory CD4+ T lymphocytes, when cultured with recall antigens." (PMID 33477692, 2021). "The chronicity of HIV-1 is caused by latent infection of long-lived memory CD4+ T cells and constitutes a major barrier towards a cure of HIV-1 infection." (PMID 34198973, 2021).
HIV-1 infection (continued). "The attributes of CD73+ CD4+ T cells, particularly IL-2 production and proliferative capacity in response to recall antigens, are notably deficient in the CD4+ T cell function of the vast majority of subjects with HIV-1 infection soon after infection." (PMID 33477692, 2021). "Previous reports showed that chronic immune activation is linked to the pathogenesis of CD4+ T cell lymphopenia in patients with HIV-1 infection." (PMID 34220854, 2021). "High levels of caspase-1 and caspase-3, and low levels of Bcl-2 in platelet-CD4+ T cell aggregates imply the potential role in CD4+ T cell loss during HIV-1 infection." (PMID 34987521, 2021). "This opposite role was also presented in chronic HIV-1 infection because the associations between CD4 T-cell counts and the amounts of these two NK subset cells were antagonistic." (PMID 33717085, 2021). "The results suggested that the presence of the IFN+874A allele confers susceptibility to HIV-1 infection and a decrease in the number of CD4+ T lymphocytes and the association of genotype 509TT of TGFβ with an increase in HIV-1 plasma viral load." (PMID 34067165, 2021). "The hallmark characteristic of HIV-1 infection is the depletion of immune cells, especially CD4+ T-cells." (PMID 34832897, 2021). "Previous studies have shown that HIV-1 infection causes downregulation of CD4 and major histocompatibility complex (MHC)-I." (PMID 34452453, 2021). "During HIV-1 infection, programmed cell death, including caspase-3-dependent apoptosis and caspase-1-dependent pyroptosis, contributes to CD4+ T cell loss and immunopathogenesis." (PMID 34987521, 2021). "Together, these results suggest that CD4+ iNKT cells represent a pool of susceptible cells in which the virus can replicate during the earliest stages of HIV-1 infection." (PMID 34753817, 2021). "One of characteristics of chronic HIV-1 infection in patients is a progressive loss of CD4 + T cells, which consequently disrupts immune responses." (PMID 33883686, 2021). "Recent studies revealed that the loss of CypA binding, by either depletion, CsA treatment, or CA mutations, led to significant restriction of HIV-1 infection by human TRIM5α in CD4+ T cells." (PMID 33758083, 2021). "A recent study in people with chronic HIV-1 infection has shown that CD8+ T cells not only responded to mutated HIV-1 epitopes which cause death of CD4+ T cells, but also led to increased maturation of cells producing higher transinfection of CD4+ T cells." (PMID 35058917, 2021). "A major function of DC is to interact with CD4 T cells and present antigen, and DC have been linked to both cell-mediated HIV-1 infection as well as the establishment of latency." (PMID 33228686, 2020). "Similar to HIV-1-specific CD4+ T cells, Mycobacterium tuberculosis (TB)-specific CD4+ T cells are preferentially depleted early during HIV-1 infection due to viral cytopathic effect and the loss of proliferation capacity due to chronic immune activation." (PMID 31910871, 2020). "During acute HIV-1 infection, a massive loss of memory CD4+ T cells throughout the body occurs, particularly in the mucosa." (PMID 32911701, 2020). "In a physiological setting, the binding of virion-associated gp120 to cellular CD4 is often weak and most cell types that are permissive for HIV-1 infection express low levels of CD4." (PMID 32485969, 2020). "Acquired immunodeficiency syndrome is caused by the progressive depletion of CD4 T cells as a consequence of HIV-1 infection." (PMID 31786265, 2020). "Recently, it was shown that the cytosolic DNA sensor cGAS is also implicated in sensing HIV-1 infection in activated CD4+ T cells." (PMID 31968566, 2020). "CCR5 is expressed on the surface of memory CD4+ T cells and causes the massive depletion of this cell type following HIV-1 infection of the host." (PMID 32154191, 2020). "It is well known that HIV-1 infection mainly attacks CD4 cells and induces progressive loss of CD4 counts." (PMID 33131455, 2020).
HIV-1 infection (continued). "Circulating iNKT cells were reduced in HIV-1 infection, most significantly the CD4+ subset, which was inversely associated with HIV-1 viral load." (PMID 31190065, 2020). "Susceptibility to HIV-1 infection requires the co-expression of CD4 and either CCR5 (R5) or CXCR4 (X4) receptors on the cellular surface." (PMID 32576602, 2020). "Compared to activated CD4+ T cells, both macrophages and DCs are less susceptible to HIV-1 infection, largely due to high expression of the restriction factor SAMHD1." (PMID 31968566, 2020). "The results suggest that loss of both colonic and peripheral blood CD161+ CD4+ cells occurs during the earliest stages of HIV-1 infection." (PMID 33322496, 2020). "Since helper CD4+ T cell decline is a hallmark of HIV-1 infection that results in immunosuppression, we also assessed this trait between the first and second passage of the hu-mouse adapted SIV strains." (PMID 32849468, 2020). "Unadjusted analyses showed that HIV-1 infection was associated with lower CD4+ iNKT cell percentages and frequency (CD4+ iNKT cells per million CD3+CD19– live lymphocytes) in patients with (P = .007) and without (P = .005) active TB." (PMID 31190065, 2020). "Alteration in CD4 counts during the treatment of HIV-1 infection is significantly associated with immune restoration, morbidity, and mortality." (PMID 33131455, 2020). "In summary, we found that HIV-1 infection was associated with iNKT cell depletion and CD4+ iNKT cell subsets were most significantly depleted in advanced HIV." (PMID 31190065, 2020). "Our findings indicate that HIV-1 infection is associated with a reduced capacity of CD161+ CD4+ T cells to produce cytokines following stimulation with IL-12 and IL-18." (PMID 33322496, 2020). "Here, we use TZM-bl and MT4 T cells that are homogeneous in metabolic state and have high glycolytic activity similar to activated CD4 T cells susceptible to HIV-1 infection." (PMID 32084246, 2020). "To analyze the susceptibility of the target cells to HIV-1 infection, we pulsed autologous CD4+ T cells from each individual with laboratory-adapted R5- and X4-tropic viral strains for 7 days." (PMID 32024974, 2020). "This is supported by the inverse association between VL and the frequency of CD161+ CD4+ T cells in both peripheral blood and colonic mucosa in the present study, as well as previous studies, indicating their high susceptibility to HIV-1 infection in vitro." (PMID 33322496, 2020). "More recently, it has been shown that basal glycolytic activity of CD4+ T cell subsets correlates with susceptibility to HIV-1 infection." (PMID 32084246, 2020). "Selective resistance of CD4+ TCM cells to HIV-1 infection has also been implicated as a mechanism of CD4+ TCM cell preservation in VNPs." (PMID 32194543, 2020). "DCs are less susceptible to HIV-1 infection than CD4+ T cells, as only around 1% of DCs are infected, and the HIV-1 infection is less productive than in CD4+ T cells." (PMID 31708924, 2019). "The pathogenesis of HIV-1 infection is linked closely to the replication of the virus in CD4+ helper T cells followed by the massive loss of CD4+ T cells in vivo." (PMID 31100082, 2019). "α4β7high CD4+ T cells are highly susceptible to HIV-1 infection and are preferentially depleted during acute HIV-1 and SIV infection." (PMID 31083697, 2019). "To determine the susceptibility of CD161+ CD4+ T cells to HIV-1 infection, we first quantified the expression level of the coreceptors CCR5 and CXCR4 from HIV-1-negative and -positive individuals receiving or not receiving ART." (PMID 31594817, 2019). "CD4+ T cell loss is observed within months of HIV-1 infection from both peripheral blood and lymphoid tissues." (PMID 30873181, 2019). "Nevertheless, these samples reflect different immune environments, such as possible differences in the relative proportions of cell types implicated in the immunopathogenesis of HIV-1 infection, i.e. resting CD4+ T cells." (PMID 31582776, 2019).
HIV-1 infection (continued). "At the peak of innate immune activation, prior to CD4 T cell loss, HIV-1 infection differentially affects peripheral and lymphoid Toll-like receptor (TLR) expression profiles in T cells and macrophages." (PMID 30867315, 2019). "Considering this, we examined the in vitro effect of the treatment of peripheral blood mononuclear cells (PBMCs) with the active form of VitD, calcitriol, on cellular activation, function and susceptibility of CD4+ T cells to HIV-1 infection." (PMID 31550271, 2019). "Higher frequencies of α4β7high CD4+ T cells have been correlated with increased susceptibility to HIV-1 infection in humans and SIV infection in macaques and with disease progression in both humans and macaques." (PMID 31083697, 2019). "In this regard, we decided to go further, exploring the in vitro role of the active form calcitriol on the susceptibility of CD4+ T cells to HIV-1 infection." (PMID 31550271, 2019). "A study comparing the effect of WT HIV-1 vs. Nef-mutated HIV-1 on the activation of resting CD4+ T cells found that Nef was required for T cell activation and productive HIV-1 infection." (PMID 31708924, 2019). "We have previously shown that the down-regulation of SAMHD1 expression during T-cell activation and differentiation renders CD4+ T cells susceptible to HIV-1 infection." (PMID 31220191, 2019). "We posit that immune-activation and inflammation explains early HIV-1 infection, rapid viral dissemination, and accelerated CD4+ T cell loss in the hu-HSC mice." (PMID 30873181, 2019). "Despite that it has been reported that CMV-specific CD4+ T cells are less susceptible to HIV-1 infection in vivo, they were still found to be susceptible to a degree." (PMID 31905690, 2019). "Peripheral CD4+ T cell loss began at 3 days together with detection of HIV-1 RNA in both mouse models after initiation of HIV-1 infection." (PMID 30873181, 2019). "We have argued that the risk of HIV-1 infection is controlled by the local concentration of CD4+ T cells and the degree of damage caused by HSV-2 within the genital tissue." (PMID 29698393, 2018). "In the present study, we reported a direct relationship between higher CD4+ T cell activation during acute HIV-1 infection and the less loss of CD4+ T cells after 2 years of acute infection (chronic infection stage)." (PMID 29636753, 2018). "For example, during HIV-1 infection, CD4+ T cells are rapidly depleted, especially in gut associated lymphoid tissue (GALT)." (PMID 30132758, 2018). "Our data suggest that a higher degree of exhausted CD4+ T cells during HIV-1 infection is partly linked to higher frequency of CD25+ FoxP3+ CD4+ T cells." (PMID 29403500, 2018). "HIV-1 infection is associated with an increase in aerobic glycolysis in CD4+ T cells, both in vitro and in patients." (PMID 30206166, 2018). "Latent HIV-1 infection in resting CD4+ T cells is the primary cause of the barrier to a functional cure." (PMID 29773895, 2018). "We then fit the risk of HIV-1 infection as a function of CD4+ cell count and the percentage of tissue damage, to produce equations similar to those given above (Eqs 1–3)." (PMID 29698393, 2018). "We found a positive association of CE with CD4+ T-cell count, secondary to the uncontrolled HIV-1-infection, even after adjusting for ApoAI levels." (PMID 30213800, 2018). "In summary, we found that higher level of CD4+ T cell immune activation in acute HIV-1 infection stage associates with subsequent slower CD4+ T cell decline in our study." (PMID 29636753, 2018). "Others and our group have previously shown that HIV-1 infection is associated with an increase in aerobic glycolysis of CD4+ T cells." (PMID 30206166, 2018). "In two settings devoid of SIV/HIV-1 infection, we show here that CD4 T cell deficiency is associated with depletion of ILCs in the blood and MLN." (PMID 30262807, 2018).